TFF1 (trefoil factor 1)
Diseases named in the same sentence as TFF1 in open-access papers (continued):
Sharing a sentence is not in itself a finding about the gene and the disease.
cancer (continued). "For practical use of serum TFF1, TFF2, and TFF3 for cancer screening, subjects who were detected to have high serum TFF3, should be scrutinized by imaging examination." (PMID 28687783, 2017). "We found that the promoter regions of TFF1 and MAGEA1 were hypomethylated in cancer compared with adjacent samples (p < 10-5) and in cancer vs. control mammoplasty samples (p < 10-4)." (PMID 26510686, 2015). "All these genes (AREG, GREB1, TFF1 and TFF3) were up-regulated in ER+ carcinomas compared to ER- carcinomas (AREG was only borderline significant)." (PMID 21812955, 2011). "Although these proteins are frequently co-expressed and act cooperatively in normal tissues, the relationship between the expression of TFF1 and MUC5AC was rather weak in cancer, since only 7% of 2289 cancer samples with TFF1 and/or MUC5AC expression expressed both proteins." (PMID 39410561, 2024). "Through negative modulation of GSK3β, MYCT1, Fascin actin-bundling protein 1 (FSCN1), and TFF1, miR-632 modulated the WNT/β-catenin pathway and subsequently promoted cancer cell migration, invasion, proliferation, tube formation, and endothelial cell recruitment." (PMID 35242169, 2022). "Other factors are involved in the interaction of cancer cells and CSC include cyclooxygenase (COX)-2 and as the conditioned environment of cancer cells increases, COX-2 expression and CSC proliferation, and Trefoil factors (TFF)-1, whose expression stimulates the proliferation and migration of CSC." (PMID 33466892, 2021). "Non-neoplastic gastric mucosa adjacent to carcinomas was present in 30 out of 31 cases and in all cases, TFF1 immunoexpression was similar to that observed in normal canine gastric mucosa (100%)." (PMID 34679875, 2021). "Fifteen out of the 23 (65.2%) carcinomas with reduced expression of TFF1 presented neoplastic emboli, but it was not statistically significant (p = 0.171)." (PMID 34679875, 2021). "In addition, our data are consistent with previously published work that showed that TFF1 and TFF2 are frequently overexpressed in several human cancers." (PMID 31216714, 2019). "The effects of TFF1 and TFF3 for cancer progression is still controversial." (PMID 28687783, 2017). "Through analyzing the methylated DNA immunoprecipitation (MeDIP) sequencing profiles available from our center and The Cancer Genome Atlas (TCGA), we identified that cg01886855 (TFF1 MS) and cg26403416 (TFF2 MS) might be the key CpG island sites separately for the TFF1/TFF2 DNA methylation." (PMID 36428568, 2022). "Reduced expression of TFF1 was more frequent, though not significantly, in poorly/undifferentiated carcinomas (80%) and, in indeterminate and diffuse type carcinomas (80% and 80%, respectively) than in well-differentiated or intestinal type carcinomas (50%, p = 0.132 and p = 0.229)." (PMID 34679875, 2021). "Importantly, only 6 (13.0%) cancers were stained by TFF1 weaker than surrounding non-cancerous epithelial tissue, and only 4 (8.7%) cancers was stained for TFF3 weaker than surrounding non-cancerous epithelial tissue." (PMID 28687783, 2017). "Consistent with expectations, canonical luminal genes such as ESR1, GATA3, FOXA1, TFF1 and IGF1R were higher in ER+ samples compared to triple negative samples, while proliferation and mesenchymal genes such as SPRY2, SNAI2, FOSL1, MET and BUB1 were higher in triple negative cancers." (PMID 24520381, 2014). "To investigate whether TFF1-dependent suppression of H. pylori-induced transcriptional activation of β-catenin leads to downregulation of β-catenin downstream targets, we assessed mRNA and protein expression of cyclin D1 and c-Myc in an in vitro MKN28 cancer cell model." (PMID 25980439, 2015). "Initially, we assessed the methylation status of TFF1 promoter in ESCC patients and subjects without cancer by pyrosequencing." (PMID 29296124, 2017).
cancer (continued). "Many E2 regulated genes in other normal and cancer cell types were also regulated in MOE cells including Pgr, Greb1, Csf2, and Dhrs9, while other E2 regulated genes in MCF7 cells were not regulated (Nrip1) or even expressed (Tff1) in MOE cells." (PMID 26879975, 2016).
infection (20 papers, 2012 to 2025). The state of being infected such as from the introduction of a foreign agent such as serum, vaccine, antigenic substance or organism. "Using conditioned media from H. pylori-activated PBMCs, we show that inflammatory signals produced during infection can repress TFF1, also in the mucosoid model of primary gastric cells." (PMID 41573568, 2025). "Our results suggest a central role for the host inflammatory response in silencing TFF1 during the later stages of infection." (PMID 41573568, 2025). "Compared to baseline levels, the median concentration of serum TFF1 was significantly elevated at week 8 (22.1 pg/mL vs. 33.9 pg/mL, p < 0.05) and week 36 (22.1 pg/mL vs. 37.5 pg/mL, p < 0.05) post-infection." (PMID 39596084, 2024). "TFF1’s role in fortifying mucosal defenses is important, suggesting a protective role against the spread and severity of the infection within the gastrointestinal tract." (PMID 39456924, 2024). "In the lung, a significant upregulation in the mRNA expression of the gel-forming mucins, Muc5ac and Muc5b, trefoil factors, Tff1 and Tff2, and Relm-β, was observed in the acute infection phase." (PMID 39596084, 2024). "Still, in a mouse model of infection, we recently demonstrated that TFF1 expression is upregulated during the acute phase of infection while gradually silenced when inflammation becomes chronic." (PMID 36514982, 2022). "Given the high host specificity and tropism of H. pylori, it is still unclear if the interaction favors the bacterium persistence in the gastric environment or prevents the damage of the infection due to the protective functions of TFF1, or both." (PMID 33673347, 2021). "The reconstitution of TFF1 significantly reduced the mRNA expression of the prior genes, compared with their corresponding control cells after infection with H. pylori." (PMID 34419066, 2021). "TFF1 is one of the mucus components, known to interact with H. pylori and to play a protective role during infection." (PMID 33673347, 2021). "We used AGS cells stably expressing TFF1 or empty vector pcDNA for infection with H. pylori 7.13 and J166 for 24 h." (PMID 34419066, 2021). "In addition, H. pylori infection of TFF1-null mice causes more severe gastric inflammation than infection of wild-type mice, which suggests that an increased number of organisms may interact with the epithelial cells if TFF1 is absent from the gastric mucus than if it is present." (PMID 31500233, 2019). "Then, expression of TFF1 is gradually silenced when the infection becomes chronic and IFN-γ, CXCL5, and CXCL15 reach higher levels." (PMID 29085807, 2017). "We report that, during the acute phase of infection, TFF1 mRNA is significantly up-regulated in the antrum while, starting from 2 weeks post-infection, its level is lowered and at 6 weeks we observe an appreciable reduction of its protein signal." (PMID 29085807, 2017). "Nonetheless, data on TFF1 role in prodromal phases of infection prior its chronic conversion are missing." (PMID 29085807, 2017). "In infected mice, TFF1 is initially upregulated in gastric antrum in the acute phase of infection, along with IL-1β and IL-6." (PMID 29085807, 2017). "Our results demonstrate that TFF1 is up-regulated in the acute phase of infection together with IL-1β and IL-6, while is down-regulated in the chronic phase of infection (after 42 days) when IFN-γ, CXCL5, and CXCL15 increase." (PMID 29085807, 2017). "TFF1 and TFF2 are up-regulated upon infection, in both doxycycline-induced and -uninduced cells, but their levels are significantly higher in TFF1 hyper-expressing cells (dox-induced)." (PMID 29085807, 2017). "Conversely, during the chronic phase of infection (at 42 days) when cellular infiltrates increase, TFF1 expression is reduced." (PMID 29085807, 2017). "We analyzed TFF1 mRNA in the very early phase of infection at 1, 3, 5, and 8 days post-infection and later at 2 and 6 weeks." (PMID 29085807, 2017).
infection (continued). "We showed that the extracellular mucus layer produced by HT29-MTX-E12 cells contains TFF1 and that after infection H. pylori organisms can be visualised within the mucus layer." (PMID 23056622, 2012). "Furthermore, the mRNA expression of TFF1 was significantly up-regulated at 48 hours post infection of PEDV (P < 0.01)." (PMID 35693767, 2022). "In addition, upon infection of E12 cells H. pylori can co-localize with TFF1 present in the adherent mucus layer and mutants unable to bind TFF1 show reduced infection of these cells." (PMID 29783620, 2018). "Of interest in the murine experimental model of H. pylori infection, the presence of TFF1 is not necessary for infection, as H. pylori has been shown to infect tff1-deficient mice." (PMID 29783620, 2018). "Interestingly, in infected mice, TFF1 is upregulated in the early phase of infection, while it is gradually silenced right after the acute injury phase." (PMID 29085807, 2017). "Based on these data, we conclude that, in our experimental conditions, when TFF1 is up-regulated (acute phase of infection), there is an innate immune response which ends at 8 days post-infection, while when TFF1 is reduced (at 6 weeks) signs of the chronic phase of infection are visible." (PMID 29085807, 2017). "Importantly, the TFF1 gene shows the tissue-specific expression pattern and is closely related to the ability of injury healing, activating the host’s resistance to pathogens infection." (PMID 35693767, 2022). "Tff1 was significantly induced after infection, which might increase the motility of immune cells." (PMID 28604600, 2017). "The finding that TFF1 may be important in mediating H. pylori colonization of the gastric mucosa suggests that we need to consider carefully the role of non mucin components of mucus in mediating infection of mucosal surfaces." (PMID 23056622, 2012). "Our study revealed that morbillivirus triggers massive upregulation of TFF1, TFF3 and, to a lesser degree, TFF2 expression, provided infection occurred during lung immune homeostasis." (PMID 38331906, 2024). "The importance of these results lies in the validation of TFF1, GSTA5, HSPA6, FOS, MPIG6B, F2 and HP not only as key markers for the presence of infection but also for their specificity in differentiating between various Mpox strains." (PMID 39456924, 2024). "Our data indicated that after infection with both strains of H. pylori (J166 and 7.13), phospho-AKT (Ser473) and AKT protein levels were decreased in TFF1 expressing cells as compared to control cells." (PMID 25980439, 2015). "pdmCA09 infection alone resulted in only slightly increased TFF1 and 2 expression 10 dpi and TFF3 was not upregulated, indicating that extreme induction of TFF1 and 3 is morbillivirus-specific rather than a general response to respiratory virus infections." (PMID 38331906, 2024). "Both cell culture infection models and non-TCGA cohort EBVaGC data have identified increased methylation of the TFF1 gene in the presence of EBV." (PMID 37112833, 2023). "Hence, we based our in vivo experiments on the hypothesis that gastric mucosa, in the acute phase of infection, tries to face bacteria by up-regulating TFF1; when infection persists and becomes chronic, other molecular mechanisms occur and lead to the silencing of TFF1, along with other genes." (PMID 29085807, 2017). "Control experiments in the presence of basal levels of TFF1 and/or the addition of copper chelator showed that copper alone was not able to modify the yield of infection, but only showed a positive synergistic effect in the presence of TFF1." (PMID 24236136, 2013). "All our infection studies were with HT29-MTX-E12 cells after 21 days of culture because at this time they had formed tight junctions and secreted a mature adherent mucus layer which contained the mucin MUC5AC and trefoil protein TFF1." (PMID 23056622, 2012).
infection (continued). "However, the absence of TFF1 resulted in severe inflammation and increased incidence of gastric tumorigenesis compared to infection with wild type mice." (PMID 29783620, 2018). "On the other hand, TFF3 is up-regulated upon infection only in TFF1 not expressing cells." (PMID 29085807, 2017). "Moreover, the presence of TFF1 might influence the regulation of TFF2 and TFF3 expression upon infection, since TFF2 turns to be more induced than expected, while TFF3 is not." (PMID 29085807, 2017). "After infection with H. pylori strains, qRT-PCR results indicated a significant decrease of mRNA expression of CCND1 (p < 0.001 for both J166 and 7.13 strains) and c-MYC (p < 0.01 and p < 0.001 for J166 and 7.13 strains, respectively) in TFF1 expressing cells as compared to control cells." (PMID 25980439, 2015). "However, in control cells, infection with H. pylori without TFF1 expression induced a significant increase of pTopFlash reporter activity as compared to uninfected cells (p < 0.01)." (PMID 25980439, 2015). "Finally, the increase in bacterial adhesion induced by TFF1 and copper in AGS-AC1 cells, unable to produce mucus, poses a further unresolved question about possible and more complex roles of the peptide in host infection." (PMID 24236136, 2013). "Indeed, H. pylori also adheres to rat and bovine mucins, but natural infections in animals other than primates do not occur, probably because of physiological conditions, LPS composition of H. pylori and molecular features of TFF1 that determine such specificity of the bacterium." (PMID 33673347, 2021).
adenocarcinoma (11 papers, 2012 to 2025). A common cancer characterized by the presence of malignant glandular cells. "Additionally, the loss of TFF1 expression leads to a cascade of gastric lesions, including low-degree dysplasia, high-degree dysplasia, and adenocarcinoma." (PMID 36428568, 2022). "Loss of TFF1 expression in the TFF1-knockout (KO) mouse leads to a pro-inflammatory phenotype with a cascade of gastric lesions that include low-grade dysplasia, high-grade dysplasia, and adenocarcinomas." (PMID 31292446, 2019). "In a mouse model, loss of TFF1 promotes gastric dysplasia and adenocarcinoma." (PMID 25015107, 2014). "In mice with TFF1 knockout (KO), the absence of TFF1 expression leads to an inflammatory phenotype and triggers a cascade of gastric lesions, including low-grade dysplasia, high-grade dysplasia, and adenocarcinoma." (PMID 39309860, 2024). "A cytological examination showed positive staining for malignant cells, which is consistent with trefoil factor (TFF)-1 adenocarcinoma metastases." (PMID 24137394, 2013). "The pathological analysis of the pleural effusion was consistent with the malignant cells from the immunohistochemical pattern, suggesting a diagnosis of adenocarcinoma (TFF1-positive, CEA-positive, CK7-positive, CK20-negative and calretinin-negative)." (PMID 24137394, 2013). "Histological analysis using H&E staining indicated a marked increase of invasive adenocarcinoma occurrence among infected Tff1-KO mice (7 out of 21, 33%) as compared to age-matched (8–15 month old mice) uninfected Tff1-KO mice (5 out of 48, 10%), using our inventory from 2009–2014." (PMID 25980439, 2015). "Malignant cells that were positive for TFF1 and carcinoembryonic antigen (CEA) expression were detected, which was suggestive of adenocarcinoma." (PMID 24137394, 2013).
kidney disease (4 papers, 2015 to 2021). "During the initial phase of renal diseases, TFF1 secretion is increased obviously by elevated urinary levels when compared to healthy probands or later CKD stages." (PMID 28355260, 2017). "Notably, among these abnormally expressed proteins, 19 proteins were reported as kidney disease markers (Ada, Ambp, Anxa1, B2m, Camp, Col1a1, Cp, Ggt1, Glb1, Lgfbp7, Lifr, Lpl, Plau, Ptgds, S100a8, Serpinc1, Serpina3k, Tff1, and Vtn) (highlight in green)." (PMID 31708494, 2019). "Hence, our findings demonstrate that TFF1 expression seems to be upregulated during the acute phase of kidney disease." (PMID 26390128, 2015). "Consequently, higher urinary TFF1 levels and the potentially co-regulated TFF2 might reflect the initial acute phase of renal diseases." (PMID 28355260, 2017).
bacterial infection (3 papers, 2017 to 2021). "On the other hand, TFF1 mRNA induction caused by bacterial infection is higher in AGS (ca. 150-fold) compared to KATO III cells (ca. 10-fold)." (PMID 29085807, 2017). "The first defensive barrier from bacterial infection is constituted by the gastric mucosa that secretes several protective factors, among which is the trefoil factor 1 (TFF1), that, as mucin 5AC, binds the bacterium." (PMID 33673347, 2021).
benign tumors (1 paper, 2024). "As TFF3 is more abundant than the other two proteins (TFF2 is usually undetectable, and TFF1 was significantly more expressed in benign tumors), we mainly focused on TFF3 expression in this study." (PMID 39256888, 2024).
cardiovascular diseases (1 paper, 2022). "Unexpectedly, we found that trefoil factor 1 (Tff1), a molecule that has not received attention in cardiovascular diseases in the past, can inhibit the apoptosis of SMCs and promote vascular repair." (PMID 35332699, 2022).
gastrointestinal disease (1 paper, 2017). A disease that occurs in the gastrointestinal system, excluding the hepatobiliary system. "In animal models TFF1 and TFF2, but not TFF3 have been shown to be upregulated during the acute phase of gastrointestinal diseases, while TFF3 reemerged during the restitution phase." (PMID 28355260, 2017).
respiratory diseases (1 paper, 2020). "The top ten genes (Clca1, Chil4, Itln1, Tff1, Muc5ac, Clca3b, Chodl, Pla2g4c, Mmp10, and Stac2) with the highest fold change are involved in various inflammatory responses and respiratory diseases." (PMID 33066398, 2020).
TFF1 also shares sentences with these, for which no sentence is quoted: esophageal squamous cell carcinoma (3 papers); Barrett esophagus (2); chronic pancreatitis (2); gastric ulcer (2); mucinous adenocarcinoma (2); acid reflux (1); adenocarcinoma of the prostate (1); adenocarcinomas of the cervix (1); aneurysm (1); bacterial vaginosis (1); colorectal adenocarcinoma (1); colorectal adenoma (1); ductal carcinoma in situ (1); duodenal ulcer (1); dysplasia (1); endometrioid carcinoma (1); esophageal cancer (1); gallbladder adenocarcinoma (1); gastrointestinal carcinomas (1); glioblastoma (1); hematological disease (1); ileitis (1); inflammation (1); invasive breast carcinoma (1); lung disease (1); lymph node metastasis (1); malignant eye tumors (1); melanoma (1); mucinous carcinomas of the ovary (1); neuroendocrine neoplasm (1).
A further 19 diseases each share a sentence with TFF1 in 1 paper.